CKLF (chemokine like factor)
Description:
May play an important role in inflammation and regeneration of skeletal muscle. Essential for embryonic development (By similarity). [Isoform 1]: Has chemotactic response in monocytes, neutrophils and lymphocytes. Binds CCR4.
Synonyms: CKLF1; HSPC224; UCK-1; CKLF3; CKLF4; C32; CKLF2
Tractability: Antibody: UniProt places it where antibodies can reach, with high confidence; its Gene Ontology location is reachable by antibodies, with high confidence; UniProt predicts a signal peptide or a membrane-spanning region. PROTAC: ubiquitination databases record sites on it.
Gene: Protein-coding gene on chromosome 16 (66,552,563 to 66,566,251, forward strand). Ensembl gene ENSG00000217555.
Subcellular location: Secreted (Isoform 1); Membrane (Isoform 2); Membrane (Isoform 4)
Subcellular location (Human Protein Atlas): Vesicles; Mid piece; Principal piece; Predicted to be secreted
Gene Ontology:
Molecular function: chemokine activity; protein binding
Biological process: lymphocyte chemotaxis; macrophage chemotaxis; neutrophil chemotaxis; secretion by cell; leukocyte chemotaxis
Cellular component: extracellular region; membrane
Genetic constraint (gnomAD): Loss-of-function variants: 16 observed, 13.87 expected, observed/expected ratio (o/e) 1.15, 90% interval 0.78 to 1.72. The upper end of that interval is the gene's LOEUF score, 1.72, which puts it in group 6 of 6, group 1 being the genes least tolerant of losing a copy. Missense variants: 172 observed, 200.78 expected, observed/expected ratio (o/e) 0.86, 90% interval 0.76 to 0.97. Synonymous variants: 61 observed, 72.03 expected, observed/expected ratio (o/e) 0.85, 90% interval 0.69 to 1.05.
Homologues: Orthologues: rabbit CKLF (80% identical), dog CKLF (74% identical), guinea pig CKLF (74% identical), rat Cklf (60% identical), mouse Cklf (58% identical), pig CKLF (56% identical), Caenorhabditis elegans F28H1.4 (14% identical), Caenorhabditis elegans F47B3.3 (12% identical). Paralogues in human: CMTM1 (39% identical), CMTM2 (24% identical), CMTM5 (19% identical), PLP2 (19% identical), CMTM3 (16% identical), CMTM7 (14% identical), PLLP (12% identical), CMTM6 (11% identical), MAL (11% identical), MALL (11% identical), MARVELD1 (11% identical), CMTM4 (10% identical), and 2 more.
Diseases named in the same sentence as CKLF in open-access papers:
CKLF is named in the same sentence as 47 diseases in open-access papers, as found by Europe PMC text mining. Sharing a sentence is not in itself a finding about the gene and the disease. The quoted sentences say what the papers report.
ischemic stroke (9 papers, 2019 to 2025). A stroke disorder caused by obstruction of blood flow to the brain, due to thrombotic (local blood clot formation) or embolic (due to a blood clot or other material traveling from another site) event. "The upregulation of chemokine-like factor 1 (CKLF1) observed in ischemic stroke positions CKLF1 as a promising therapeutic target." (PMID 40365317, 2025). "M1 macrophage and microglial polarization in ischemic stroke are partially dependent on CCR4 via the chemokine‐like factor 1 (CKLF1)‐mediated NF‐κB pathway." (PMID 37452512, 2023). "Chemokine-like factor 1, CKLF1, is a potential target for the treatment of ischemic stroke." (PMID 35008558, 2021). "IMM-H004, a novel coumarin derivative, could decrease the expression level of chemokine-like factor 1 (CKLF1) combining with C-C chemokine receptor 4, further inhibiting the NLRP3 inflammasome activation and inflammation, thereby exerting therapeutic effects on rats following ischemic stroke." (PMID 32581721, 2020).
Stroke (8 papers, 2014 to 2025). Sudden impairment of blood flow to a part of the brain due to occlusion or rupture of an artery to the brain. "Despite low exposure in vivo, M1 had an IC50 value of 2.12 × 10−8 M as an antagonist of the potent stroke target chemokine-like factor 1 in previous research." (PMID 31249524, 2019).
keloid (5 papers, 2020 to 2025). An irregularly shaped, elevated mark on the skin caused by deposits of excessive amounts of collagen during wound healing. "Various pro‐inflammatory cytokines, including IL‐6, IL‐8, IL‐18 and chemokine like factor‐1 (CKLF‐1), are significantly elevated in keloid tissue, and IL‐8 and IL‐17 are elevated in the peripheral blood of keloid patients." (PMID 39895409, 2025). "A plethora of factors including IL-6, IL-8, IL-18, chemokine like factor-1 (CKLF-1), prostaglandin produced by cyclooxygenase (COX-1) that exhibit pro-inflammatory roles upon tissue damage have been found significantly elevated in keloid tissue." (PMID 33343575, 2020).
psoriasis (5 papers, 2015 to 2025). An autoimmune condition characterized by red, well-delineated plaques with silvery scales that are usually on the extensor surfaces and scalp. "Previously, the C-terminal peptide of chemokine-like factor 1 (CKLF1) has demonstrated protective effects against psoriasis by inhibiting the MAPK pathway and reducing inflammation." (PMID 40299379, 2025). "Chemokine-like factor 1 (CKLF1), a human cytokine that is a functional ligand for CCR4, displays chemotactic activities in a wide spectrum of leukocytes and plays an important role in psoriasis development." (PMID 29066845, 2017).
asthma (4 papers, 2014 to 2022). "The enhanced CKLF expression was observed to associate with excess production of numerous inflammatory cytokines and graver autoimmune injury in rheumatoid arthritis and asthma." (PMID 36309899, 2022).
atherosclerosis (3 papers, 2023 to 2025). A disease characterized by the build-up of fatty material and calcium deposition in the arterial wall resulting in partial or complete occlusion of the arterial lumen. "Using the hypergeometric distribution model and 33 RA-related genes linked with CKLF (p < 0.05), some inflammation- or immune-related pathways were also observed, such as “IL-17 signaling pathway” and “Fluid shear stress and atherosclerosis”." (PMID 40569958, 2025). "Chemokine-like factor 1 (CKLF1) and chemokine receptor-8 (CCR8) have been shown to play an essential role in the migration and proliferation of VSMCs in vascular inflammation, and inhibition of CKLF1 can be used as a therapeutic target for the prevention of atherosclerosis." (PMID 39744707, 2024).
autoimmune disease (2 papers, 2020 to 2022). A disorder resulting from loss of function or tissue destruction of an organ or multiple organs, arising from humoral or cellular immune responses of the individual to their own tissue constituents. "Chemokine-like factor (CKLF)-like MARVEL transmembrane domain-containing family (CMTM) members are implicated in autoimmune diseases, male infertility and various tumors." (PMID 35986302, 2022).
brain injury (2 papers, 2014 to 2024). Acute and chronic (see also brain INJURIES, CHRONIC) injuries to the brain, including the cerebral hemispheres, CEREBELLUM, and brain STEM. "Chemokine‐like factor 1 (CKLF1) may be involved in the inflammatory response and secondary brain injury after severe traumatic brain injury (sTBI)." (PMID 38773776, 2024).
glioma (2 papers, 2017 to 2022). A benign or malignant brain and spinal cord tumor that arises from glial cells (astrocytes, oligodendrocytes, ependymal cells). "The result indicated that the levels of CMTM3, CMTM6, CMTM7, CMTM8, and CKLF were much higher in IDH-WT than in IDH-mutated gliomas in the TCGA database (p < 0.001)." (PMID 35252165, 2022). "Results showed that the expression level of CMTM1, CMTM3, CMTM6, CMTM7, CMTM8, and CKLF was elevated in high-grade gliomas (grade III; p < 0.01)." (PMID 35252165, 2022). "It has been reported that the expression of SNRPN, SNRPF, and CKLF was abnormal in gliomas or other tumors." (PMID 29371935, 2017). "It has been reported that expression of SNRPN, SNRPF and CKLF is abnormal in glioma tissues." (PMID 29371935, 2017). "In this study, it was found that CMTM6, CMTM7, CMTM8, and CKLF were highly expressed in grade III and IDH-WT gliomas." (PMID 35252165, 2022). "As illustrated, the expression of CMTM3, CMTM6, CMTM7, CMTM8, and CKLF in Grade II and III gliomas showed similar tendency as that in TCGA and CGGA databases." (PMID 35252165, 2022). "According to the abnormal protein level in high and low degree glioma, and mass spectra (MS) result after UCH-L5 overexpression, SNRPF, SNRPN and CKLF were as potential target genes of UCH-L5." (PMID 29371935, 2017).
brain tumors (1 paper, 2024). "Chemokine-like factor (CKLF) like MARVEL Transmembrane domain-containing protein 4 (CMTM4) is a tumor suppressor protein, and it reduces tumorigenesis in colorectal, renal, and brain tumors." (PMID 38927885, 2024).
colon cancer (1 paper, 2016). "In a cohort of early stage colon cancer (n=460), we examined, in silico, changes in gene expression within the CMS1 subtype and demonstrated for the first time the favorable prognostic value of chemokine-like factor (CKLF) gene expression in the adjuvant disease setting [HR=0.18, CI=0.04-0.89]." (PMID 27153559, 2016).
colorectal tumor (1 paper, 2016). "In addition, using transcription profiles originating from cell sorted CRC tumors, we delineated the source of CKLF transcription within the colorectal tumor microenvironment to the leukocyte component of these tumors." (PMID 27153559, 2016).
glioblastoma (1 paper, 2012). The most malignant astrocytic tumor (WHO grade IV). "Glioblastoma expresses the immune markers in CD73/NT5E (5′ nucleotidase, ecto), and CKLF." (PMID 23251904, 2012).
neutropenia (1 paper, 2023). A decrease in the number of neutrophils found in the blood. "In this study, expression of CKLF and the content of neutrophils were increased, with a positive correlation, indicating that CKLF may play a role in the process of neutropenia." (PMID 37063890, 2023).
osteosarcoma (1 paper, 2024). A usually aggressive malignant bone-forming mesenchymal neoplasm, predominantly affecting adolescents and young adults. "Moreover, one study integrating scRNA-seq, microarray, and bulk RNA-seq data identified tumor stem cell-related genes associated with survival, TME, and immune infiltration status in osteosarcoma, such as CKLF, DKK1, and Myc." (PMID 39324133, 2024).
pancreatic adenocarcinoma (1 paper, 2022). "used the risk score method to identify 3 genes associated with adverse prognosis of pancreatic adenocarcinoma (PAAD), ERAP2, CKLF and EREG, and constructed a nomogram based on clinical features and risk score for individualized prognosis prediction." (PMID 35757399, 2022).
viral hepatitis (1 paper, 2020). An acute or chronic inflammation of the liver parenchyma caused by viruses. "DNA hypomethylation of DCAF4L2, CKLF and UBE2C was observed in both NASH-related and viral hepatitis-related HCCs, whereas that of TRIM4, PRC1 and TUBA1B occurred in a NASH-related HCC-specific manner." (PMID 32685988, 2020).
tumor (16 papers, 2015 to 2024). "Assessment of the expression profiles according to the cell of origin confirmed that CKLF is significantly associated with tumor infiltrating leukocytes (p<0.005) when compared to the other cell types represented within the TME." (PMID 27153559, 2016). "In addition, our data also demonstrated that CKLF expression was positively correlated with dendritic cells, tumor-associated macrophages (TAMs), and Th2 and Th1 cells." (PMID 36975415, 2023). "Previous studies were consistent with the results of immune infiltration analysis in our study, suggesting that CKLF is closely associated with immune regulation, which may contribute to promote tumor proliferation and metastasis of HCC." (PMID 36975415, 2023). "To explore the effects of the CKLF expression in the tumor microenvironment, we first analyzed the correlation between the expression of CKLF and immune cell infiltration." (PMID 36975415, 2023). "Our study sheds light on the potential role of CKLF in tumor immunology and its potential to serve as a tumor biomarker and a new therapy target of HCC." (PMID 36975415, 2023). "For instance, previous studies have found that CKLF was upregulated in HCC tissues and was associated with tumor stage and patient survival." (PMID 36975415, 2023). "Several of these genes, including KITLG, CCL14, and CKLF, are cytokines, which possibly provide a mechanism for gene dysregulation in tumor cells to affect the immune phenotype." (PMID 31480259, 2019). "Using mean expression of the three probesets representing CKLF, we stratified tumor profiles across all CMSs into high, medium and low, based on CKLF gene expression." (PMID 27153559, 2016). "The only gene disconnected from this block at T3 was CMTM5—a gene belonging to the chemokine-like factor gene superfamily with putative tumor suppressor activity." (PMID 25938420, 2015). "As tumor grade increased, the mRNA expression of CKLF, CMTM1, CMTM3, and CMTM7 tended to be higher." (PMID 36975415, 2023). "Further to this, we confirmed that CKLF gene expression is confined to distinct immune subsets in whole blood samples and primary cell lines, highlighting CKLF as a potential immune cell-derived factor promoting tumor immune-surveillance of nascent neoplastic cells, particularly in CMS1 tumors." (PMID 27153559, 2016). "The chemokine-like factor (CKLF)-like Marvel transmembrane domain-containing (CMTM) family is widely expressed in the immune system and can modulate tumor progression." (PMID 35252165, 2022). "Chemokine-like factor (CKLF)-like MARVEL transmembrane domain-containing 1 (CMTM1) was upregulated in testis and many tumor tissues, and also raised cell proliferation rates and resistance to tumor necrosis factor-α (TNF-α)-induced apoptosis." (PMID 34408975, 2021). "Given the distinct structure of the tumor microenvironment (TME) within the CMS1 tumors, we sought to determine if the precise origin of CKLF gene expression was confined to any specific cell type within the TME." (PMID 27153559, 2016). "CMTM4 is the most conserved member of this family and forms a gene cluster with CKLF and CMTM1-3 on chromosome 16q22.1, a locus that is frequently deleted or modified in multiple tumours and that harbours a number of tumour suppressor genes." (PMID 26474560, 2015). "The expression of CKLF, CMTM1, CMTM3, and CMTM7 was correlated with cancer stage and tumor grade." (PMID 36975415, 2023). "Human chemokine like factor (CKLF)-like MAL and related proteins for vesicle trafficking transmembrane, domain-containing member 5 (CMTM5) has been shown to involved and may function as a tumour suppressor in tumorigenesis." (PMID 29213215, 2017).
cancer (10 papers, 2020 to 2025). A tumor composed of atypical neoplastic, often pleomorphic cells that invade other tissues. "Recent findings have also demonstrated the association of two proteins members of the chemokine-like factor (CKLF)-like MARVEL (CMTM) family with the stability of PD-L1 expression in cancer and in normal myeloid cells in both humans and mice." (PMID 39062968, 2024). "However, few studies have investigated associations between CKLF and cancer." (PMID 37306188, 2023). "The chemokine-like factor (CKLF)-like MARVEL transmembrane domain-containing family (CMTMs) is reported to be entangled in many human cancers." (PMID 40179060, 2025). "Chemokine-like factor (CKLF)–like MARVEL transmembrane domain containing 6 (CMTM6) can be observed in various cancers, but its part in OV remains little known." (PMID 35174213, 2022). "The human chemokine-like factor (CKLF)-like MARVEL transmembrane-domain-containing family (CMTM) plays an important role in human cancer, and CMTM4 is the most conserved member in the CMTM family." (PMID 35220395, 2022). "To further confirm the bioinformatics analysis results and determine the correlation between CKLF expression and HCC, we first compared the expression of CKLF in cancer tissues and adjacent tissues taken from 41 HCC patients." (PMID 36975415, 2023). "The Chemokine-like factor (CKLF)-like MARVEL transmembrane domain-containing (CMTM) family, comprising nine members, is involved in the tumorigenesis and progression of various cancers." (PMID 36975415, 2023). "The mRNA expression of CKLF, CMTM1, CMTM3, CMTM4, and CMTM7 was correlated with the cancer stage, revealing that patients with more advanced cancer stages tended to have higher mRNA expression of the CMTM family." (PMID 36975415, 2023).
infection (1 paper, 2024). The state of being infected such as from the introduction of a foreign agent such as serum, vaccine, antigenic substance or organism. "The significantly downregulated genes (NEAT1, TPM3, ZNHBA, CKLF, and OSBPL8) and the upregulated genes (ITMZC, IFNG, CD69, DNAJB9, and LYST) in NCAM1+FCGR3A+dNK cells after infection were also analyzed." (PMID 38730500, 2024).
CKLF also shares sentences with these, for which no sentence is quoted: Cerebral ischemia (7 papers); ischemia (5); colorectal cancer (3); hepatocellular carcinoma (3); injury (2); ovarian carcinoma (2); airway hyperresponsiveness (1); allergic asthma (1); Arthritis (1); atopic dermatitis (1); brain infarction (1); Cognitive impairment (1); Encephalocele (1); inflammation (1); leukemia (1); lung fibrosis (1); malaria (1); male infertility (1); melanoma (1); mental retardation (1); pancreatic cancer (1); rectal tumor (1); rheumatic diseases (1); rheumatoid arthritis (1); Sepsis (1); sex development disorders (1); subdural hematoma (1).